SAMHD1 (SAM and HD domain containing deoxynucleoside triphosphate triphosphohydrolase 1)
Diseases named in the same sentence as SAMHD1 in open-access papers (continued):
Sharing a sentence is not in itself a finding about the gene and the disease.
aneurysm (2 papers, 2017 to 2024). Bulging or ballooning in an area of an artery secondary to arterial wall weakening. "Moyamoya and aneurysms with an associated (as yet undefined) risk of intracerebral haemorrhage and infarcts, a particular feature of SAMHD1-related disease." (PMID 39424561, 2024). "An auto-inflammatory syndrome consequent to SAMHD1 mutations involves cerebral vasculopathy characterized by multifocal stenosis and aneurysms within large arteries, moyamoya, chronic ischemia, and early-onset strokes (SAMS)." (PMID 28289923, 2017). "A second genotype-specific presentation is of occlusive cerebrovascular disease (stenosis, aneurysms, moyamoya) as a feature of SAMHD1 (SAM and HD domain containing deoxynucleoside triphosphate triphosphohydrolase)-related disease, sometimes in the absence of any other stigmata." (PMID 39424561, 2024).
arbovirus infection (2 papers, 2019 to 2025). A viral infection that is transmitted by an arthropod. "Our data also provide novel evidence on the role of SAMHD1 in arbovirus infection of human skin cells." (PMID 30959732, 2019). "The results reported here therefore open new perspectives for the study of the precise role of SAMHD1 in arbovirus infection." (PMID 30959732, 2019). "Together, these results suggest that IFITs are involved in the restriction of replication of CHIKV and ZIKV and provide, as yet unreported, evidence for a proviral role of SAMHD1 in arbovirus infection of human skin cells." (PMID 30959732, 2019).
brain haemorrhages (2 papers, 2023 to 2025). "Early post-natal brain haemorrhages have been described for Aicardi-Goutières syndrome 5 (AGS5) caused by recessive variants of the viral restriction factor SAMHD1." (PMID 40406995, 2025).
clear cell renal cell carcinoma (2 papers, 2023 to 2025). "Sunho An at Seoul National University, South Korea, and co-workers examined the role of the SAMHD1 protein in the promotion and metastasis of renal clear cell carcinoma." (PMID 37009792, 2023). "Here, we aimed to investigate the oncogenic role of SAMHD1 in human clear cell renal cell carcinoma (ccRCC), particularly as a core molecule promoting cancer cell migration." (PMID 37009792, 2023). "This study aimed to elucidate the mechanism by which SAMHD1 regulates cell migration in clear cell renal cell carcinoma (ccRCC)." (PMID 37009792, 2023). "One study suggests SAMHD1 expression promotes focal adhesion kinase (FAK) signaling by binding to cortactin, and in turn activated Rac family small GTPase 1 (Rac1)-mediated lamellipodia formation in human clear cell renal cell carcinoma." (PMID 41280104, 2025).
colon adenocarcinoma (2 papers, 2022 to 2023). "Additionally, mutations associated with colon adenocarcinoma (V133I, A338T, R266H, and D497Y) were shown to reduce the dNTPase activity of SAMHD1 (see previous section)." (PMID 34480199, 2022). "In addition, co-localization of USP7 and SAMHD1 was identified in colonic adenocarcinoma tissues while this phenomenon was only rarely observed in peritumoral tissues." (PMID 37081042, 2023).
head and neck cancer (2 papers, 2019 to 2024). A primary or metastatic malignant neoplasm affecting the head and neck. "We investigated the expression levels of SAMHD1 at the RNA and protein levels in a panel of HPV16-negative and -positive head and neck cancer cell lines." (PMID 31391281, 2019). "Finally, we demonstrate that in head and neck cancer cell lines with HPV16 episomal genomes, endothall attenuates their growth and promotes recruitment of SAMHD1 to the viral genome." (PMID 39194246, 2024). "Finally, we demonstrate that the head and neck cancer cell line, SCC-104, which contains episomal HPV16 genomes, is hypersensitive to endothall, and treatment resulted in increased SAMHD1 and E2 recruitment to the replicating HPV16 genomes." (PMID 39194246, 2024). "Finally, we demonstrate that the phosphatase inhibitor endothall promotes hyper-recruitment of endogenous SAMHD1 to HPV16 replicating DNA and can attenuate the growth of both HPV16-immortalized human foreskin keratinocytes (HFKs) and HPV16-positive head and neck cancer cell lines." (PMID 39194246, 2024).
juvenile dermatomyositis (2 papers, 2023 to 2026). Juvenile dermatomyositis (JDM) is the early-onset form of dermatomyositis (DM), a systemic, autoimmune inflammatory muscle disorder, characterized by proximal muscle weakness, evocative skin lesion, and systemic manifestations. "In this case report, we presented a rare association of juvenile dermatomyositis and AGS type with new variants in the SAMHD-1 gene." (PMID 37371788, 2023).
malignant glioma (2 papers, 2019 to 2022). A grade III or grade IV glioma arising from the central nervous system. "Therefore, we evaluated SAMHD1 expression in malignant gliomas." (PMID 36139652, 2022). "Thus, we investigated whether SAMHD1 depletion could sensitize malignant glioma cells to TMZ." (PMID 36139652, 2022). "Despite a transient increase in mRNA, type I IFN did not increase SAMHD1 protein expression in primary human dendritic cells, macrophages, or CD4+ T cells, but IFN induced SAMHD1 expression in cell lines such as HEK 293T, HeLa, and U87 malignant glioma." (PMID 31600877, 2019). "Interestingly, less aggressive brain tumors, such as astrocytoma and oligodendroglioma, showed lower SAMHD1 expression than GBM, the most aggressive malignant glioma characterized by a much higher proliferation rate." (PMID 36139652, 2022). "Despite a transient increase in mRNA, type I IFNs did not enhance SAMHD1 protein expression in human primary dendritic cells, macrophages, or CD4+ T cells, but type I IFNs induced SAMHD1 expression in cell lines such as HEK 293T, HeLa, and U87 malignant glioma." (PMID 31600877, 2019).
type 1 interferonopathies (2 papers, 2023 to 2025). "Intracranial calcifications, cerebral atrophy, and leukodystrophy should alert physicians to spondylo‐enchondro‐dysplasia with immune dysregulation, ADAR1 deficiency, SAMHD1 deficiency, and type 1 interferonopathies." (PMID 37102642, 2023).
amyotrophic lateral sclerosis (1 paper, 2017). Amyotrophic lateral sclerosis (ALS) is a neurodegenerative disease characterized by progressive muscular paralysis reflecting degeneration of motor neurons in the primary motor cortex, corticospinal tracts, brainstem and spinal cord. "As with SAMHD1 loss of function, gain-of-function mutations in SOD1 are associated with neuroinflammation and degeneration, clinically manifesting as amyotrophic lateral sclerosis, which is likely a result of toxic protein aggregates." (PMID 28061811, 2017).
B cell lymphoma (1 paper, 2022). "Indeed, high SAMHD1 expression in B cell lymphoma cell lines confer resistance to cytarabine in vitro." (PMID 34738194, 2022).
Cerebral atrophy (1 paper, 2021). Atrophy (wasting, decrease in size of cells or tissue) affecting the cerebrum. "Aicardi-Goutières (AGS) is a rare immune dysregulated disease due to mutations in TREX1, RNASEH2A, RNASEH2B, RNASEH2C, SAMHD1, ADAR1 or IFIH1, characterized by encephalopathy, dystonia, basal ganglia calcifications, white matter abnormalities, and cerebral atrophy." (PMID 33482855, 2021).
chilblain lupus (1 paper, 2016). "Mutations in SAMHD1 have also been reported in a few families affected by chilblain lupus with and without central nervous system involvement (CHBL2, OMIM 614415)." (PMID 27260006, 2016).
chronic lymphoid leukemia (1 paper, 2022). "Most cancer-related studies have focused on the role of somatic alternations in SAMHD1; however, a study of chronic lymphoid leukemia (CLL) proposed an oncogenic role of germline SAMHD1 variation mediated by DNA repair mechanisms." (PMID 36199081, 2022).
diabetic foot ulcers (1 paper, 2025). "Utilizing enrichment analysis from the DSigDB database, we focused on the core genes associated with diabetic foot ulcers (DFU), specifically SAMHD1 and DPYSL2, to identify potential drug candidates." (PMID 40487403, 2025). "This study employed machine learning techniques to identify four key genes—DPYSL2, CIB2, IFI44, and SAMHD1—that potentially play a significant role in the pathogenesis and progression of diabetic foot ulcer (DFU) disease." (PMID 40487403, 2025). "Bioinformatics analyses have demonstrated that the expression levels of SAMHD1 mRNA are significantly reduced in patients with diabetic foot ulcers (DFU) compared to healthy individuals, a finding corroborated by experimental data." (PMID 40487403, 2025). "Quercetin may enhance the healing of diabetic foot ulcers by modulating macrophage activity through the regulation of SAMHD1 and DPYSL2, thereby contributing to the recovery process." (PMID 40487403, 2025).
dyslipidemia (1 paper, 2026). "In vitro, mimicking MASLD-associated dyslipidemia with palmitic acid, oleic acid, and cholesterol upregulated SAMHD1 expression, an IFN-γ-induced protein, accompanied by increased IFN-γ receptor 1 expression and STAT1 activation in HepG2 cells." (PMID 41522335, 2026). "Taken together, dyslipidemia- and inflammation-induced upregulation of IFN-γ receptor, along with elevated IFN-γ in MASLD, likely drive SAMHD1 upregulation in hepatocytes." (PMID 41522335, 2026).
Hepatitis (1 paper, 2019). Inflammation of the liver. "Regarding the antiviral effect of dasatinib, it is important to mention that the role of the cellular restriction factor SAMHD1 is not restricted to RNA viruses but to DNA viruses including poxviruses, herpes simplex 1, and hepatitis B." (PMID 31619990, 2019).
HTLV infection (1 paper, 2020). "The choice of the SAMHD1 rs6029941 polymorphism (A/G) was based on its influence on changes in gene expression and because it has not yet been evaluated for HIV and HTLV infection." (PMID 32656092, 2020).
infiltrating ductal carcinoma (1 paper, 2024). "Within the whole cohort, 11% of cases received NACT (n = 228) and SAMHD1 expression was evaluated in all infiltrating ductal carcinoma cases with follow-up (n = 182) that do not achieve pCR (n = 151)." (PMID 37667113, 2024).
inflammatory disease of the brain (1 paper, 2014). "In 2009, we identified mutations in SAMHD1 to cause a subtype of AGS, an inflammatory disease of the brain and skin associated with an upregulation of type I interferon signaling." (PMID 25278816, 2014).
influenza (1 paper, 2021). An acute viral infection of the respiratory tract, occurring in isolated cases, in epidemics, or in pandemics; it is caused by serologically different strains of viruses (influenzaviruses) designated A, B, and C, has a 3-day incubation period, and usually lasts for 3 to 10 days. "Because CCL5 showed, in conjunction, the best results for influenza inhibition and SAMHD1 enhancement levels, we selected this β-chemokine to continue the study." (PMID 34490131, 2021).
liver steatosis (1 paper, 2026). "AAV-mediated overexpression of SAMHD1 exacerbated lipid accumulation through SREBP1/2 activation, while hepatocyte-specific SAMHD1 knockout mice revealed that SAMHD1 deficiency alleviates liver steatosis." (PMID 41522335, 2026). "Induced by lipids and IFN-γ, SAMHD1 promotes lipid droplet accumulation, worsening liver steatosis and injury in diet-induced MASLD models through activation of the SREBP1 and SREBP2 pathways." (PMID 41522335, 2026). "Collectively, these findings identify hepatocyte SAMHD1 as a promoter of liver steatosis through SREBP activation and highlight it as a potential therapeutic target for MASLD." (PMID 41522335, 2026). "In vivo, hepatocyte-specific SAMHD1 overexpression increased liver steatosis, while hepatocyte-specific SAMHD1 knockout alleviated liver steatosis and injury in a GAN diet-induced MASLD model." (PMID 41522335, 2026). "Oil Red O staining and IHC for F4/80 and CD68 revealed reduced liver steatosis and decreased macrophage activation and infiltration in HKO mice at both time points, emphasizing the protective role of SAMHD1 deficiency against hepatic lipid accumulation and inflammation." (PMID 41522335, 2026).
lung large cell carcinoma (1 paper, 2020). A poorly differentiated non-small cell lung carcinoma composed of large polygonal cells without evidence of glandular or squamous differentiation. "SAMHD1 was clearly detected in at least two cancer tissue types susceptible to being treated with antimetabolites—pancreatic adenocarcinoma and lung large cell carcinoma." (PMID 32197329, 2020).
lupus nephritis (1 paper, 2023). Glomerulonephritis in the context of systemic lupus erythematosus. "Collectively, our findings support the protective role of Klotho in attenuating lupus nephritis through the inhibition of IFNγ-induced SAMHD1 expression and IFNγ downstream signaling in MES-13 cells." (PMID 37213666, 2023). "Our results indicated that the participation of Klotho in lupus nephritis may be partially attributed to its inhibitory effect on IFNγ-induced SAMHD1 expression and NFκB activation in MES-13 cells." (PMID 37213666, 2023). "The present study verified the effect of IFNγ on SAMHD1 and Klotho expression in MES-13 glomerular mesangial cells, a special cell type in glomerulus that is critically involved in lupus nephritis." (PMID 37213666, 2023).
myelodysplastic syndrome (1 paper, 2022). A clonal hematopoietic disorder characterized by dysplasia and ineffective hematopoiesis in one or more of the hematopoietic cell lines. "For the deoxycytidine analogue and DNMT1 inhibitor decitabine, clinically used in myelodysplastic syndrome (MDS) and AML, SAMHD1 expression also correlates with clinical outcome of patients receiving this therapy." (PMID 35583750, 2022).
myositis (1 paper, 2026). "SAMHD1 deficiency may manifest with isolated myositis, panniculitis or lupus-like disease, underscoring the importance of a phenotype-driven rather than genotype-based diagnostic approach." (PMID 41496005, 2026).
Obesity (1 paper, 2026). Accumulation of substantial excess body fat. "Obesity induces inhibitory phosphorylation of SAMHD1, resulting in cytosolic dNTP accumulation, mitochondrial import through SLC25 transporters, uncontrolled mtDNA synthesis and oxidation, and consequent NLRP3 hyperactivation." (PMID 42112341, 2026).
osteosarcoma (1 paper, 2019). A usually aggressive malignant bone-forming mesenchymal neoplasm, predominantly affecting adolescents and young adults. "In human carcinoma and osteosarcoma cell lines, SAMHD1 overexpression decreased the efficacy of DSB-inducing drugs such as topoisomerase inhibitors or IR, while SAMHD1 depletion was associated with increased efficacy of these treatments." (PMID 31375673, 2019).
ovarian tumors (1 paper, 2023). "Interestingly, SAMHD1 expression was significantly associated with tumor histology, being high-grade serous histology ovarian tumors those presenting the highest proportion of SAMHD1, as previously reported in other cancer types." (PMID 36845138, 2023).
primary immunodeficiencies (1 paper, 2025). "This is supported by the fact that among the 38 interferon response genes (category II), only OAS1, ADAR, PSMB8, SAMHD1 and the IRF transcription factors have been implicated in causing primary immunodeficiencies." (PMID 41038828, 2025).
rectal cancer (1 paper, 2022). A primary or metastatic malignant neoplasm that affects the rectum. "Our data do not differ from that available in public databases, except for rectal cancer, where in our series SAMHD1 was strongly expressed in all neoplastic cells." (PMID 35158911, 2022).
rhabdomyosarcoma (1 paper, 2022). A rare aggressive malignant mesenchymal neoplasm arising from skeletal muscle. "Previous research has reported that the TRIM21 E3 ubiquitination ligase mediates the degradation of SAMHD1 to facilitate EV71 infection of rhabdomyosarcoma RD cells and 293 T cells." (PMID 35803902, 2022).
Sepsis (1 paper, 2023). Sepsis is defined as life-threatening organ dysfunction caused by a dysregulated host response to infection. "In our study, the results unveiled that SAMHD1 was upregulated in LPS-stimulated wild-type macrophages, suggesting that it may play a role in the pathological process of sepsis." (PMID 37175593, 2023). "In addition, we identified H238/D239 and T634 on mouse SAMHD1 as two key targets that regulate its anti-sepsis function." (PMID 37175593, 2023). "Therefore, SAMHD1 is a potential target molecule against sepsis." (PMID 37175593, 2023). "However, little is known about whether SAMHD1 is involved in bacterial infection and sepsis." (PMID 37175593, 2023).
steatosis (1 paper, 2026). Increased lipid within the cytoplasm of cells. "Conversely, hepatocyte-specific SAMHD1 knockout reduced steatosis and liver injury in diet-induced MASLD mouse models." (PMID 41522335, 2026). "Western blot, qPCR, and IHC analyses revealed upregulation of SAMHD1 expression in the HCM diet group compared to NC-fed controls, with levels rising in parallel with the development of steatosis." (PMID 41522335, 2026). "Our data also show that SAMHD1 promotes steatosis in MASLD, with hepatic SAMHD1 expression correlating with steatosis severity in diet-induced MASLD mouse models." (PMID 41522335, 2026). "In conclusion, hepatic SAMHD1 expression is elevated in MASLD and is closely correlates with the severity of steatosis." (PMID 41522335, 2026). "Western blot, qPCR, and IHC analyses revealed elevated hepatic SAMHD1 expression in the GAN diet group compared to normal chow (NC)-fed controls, with expression levels progressively rising alongside the development of hepatic steatosis." (PMID 41522335, 2026).
T-cell immunodeficiency (1 paper, 2022). A broad classification of disorders that affect the cell-mediated aspect of the immune response. "The synthetic lethal interaction between PNP and SAMHD1 inactivation explains one of the enduring mysteries regarding the mechanisms responsible for T cell immunodeficiency in patients with PNP-inactivating mutations." (PMID 35653193, 2022).